AXL (AXL receptor tyrosine kinase)
Diseases named in the same sentence as AXL in open-access papers (continued):
Sharing a sentence is not in itself a finding about the gene and the disease.
lung cancer (continued). "Together, AXL-induced growth signaling was associated with SRC and AKT activation in osimertinib-resistant lung cancer." (PMID 35643725, 2022). "In the present study, we observed high AXL expression in lung cancer tissues, whereas its expression in twenty-two kinds of normal tissues was limited." (PMID 36261437, 2022). "AXL is overexpressed and has been investigated as a therapeutic target in several cancer types, including lung cancer." (PMID 36261437, 2022). "Considering that AXL is highly expressed in lung cancer and impacts therapeutic response, we further analyzed the effects of NT157 on this target." (PMID 36224313, 2022). "Recent studies report that the blockade of TGF-β/TβR, Wnt/β-catenin, and AXL/Gas6 signaling can potentially reduce the EGFR-TKI resistance in lung cancer A549, HCC827, and PC9 cell lines." (PMID 36547898, 2022). "R273C was also suggested to regulate the expression of AXL through histone acetylation in lung cancer cells." (PMID 36429043, 2022). "Our study revealed that the YAP signature, which was highly enriched in mesenchymal‐type lung cancer, was closely correlated to AXL expression in 181 lung cancer cell lines." (PMID 33207077, 2021). "Activation of the kinase AXL induces EGFR-TKI resistance associated with the mesenchymal phenotype, and the dual blockade of MEK and AXL overcomes EMT-mediated drug resistance and synergistically suppresses tumor growth in KRAS-mutated lung cancer cells." (PMID 34885068, 2021). "AXL and SERPINE1 were associated with downstream YAP signals via transcriptome analysis of doxorubicin‐resistant and mesenchymal‐type lung cancer cells; therefore, we investigated the effect of the knockdown of each gene on invasiveness or chemoresistance." (PMID 33207077, 2021). "In this study, we used a doxorubicin‐resistant isogenic pair of lung cancer cell lines to demonstrate that YAP activation in mesenchymal‐type lung cancer cells induced AXL expression upon doxorubicin treatment and contributed to doxorubicin resistance." (PMID 33207077, 2021). "AXL induction in mesenchymal‐type lung cancer cells upon doxorubicin treatment was induced by the elevated nuclear translocation of YAP and subsequent increase in YAP transactivation." (PMID 33207077, 2021). "MERTK and AXL mediate multiple oncogenic phenotypes in lung cancer, including tumor cell growth, survival, metastasis, invasion, and drug resistance, and are potential targets for lung cancer treatment." (PMID 34830794, 2021). "As determined by our isogenic cell‐line model, AXL expression in mesenchymal‐type lung cancer cells, which confers doxorubicin resistance, was upregulated by YAP/TAZ activity primed by the TGFβ‐SMAD axis." (PMID 33207077, 2021). "Particularly, the activation of TGFβ signaling through SMAD4 after doxorubicin treatment contributed to YAP‐dependent AXL expression in mesenchymal‐type lung cancer cells." (PMID 33207077, 2021). "This priming effect of the TGFβ‐SMAD4 axis toward YAP/TAZ‐dependent AXL expression was also validated via a meta‐analysis of lung cancer patient clinical data." (PMID 33207077, 2021). "Upregulation of the TGFβ/SMAD pathway primes YAP‐dependent AXL expression upon doxorubicin treatment to promote chemoresistance in mesenchymal‐type lung cancer cells." (PMID 33207077, 2021). "Our lung cancer xenograft data indicate that the link between AXL activation and gefitinib resistance can be specific only to tumors with prior CTD resistance." (PMID 33850249, 2021). "Increased DNA damage response following AXL inhibition has been reported for breast, ovarian, and lung cancer cell lines." (PMID 34948046, 2021). "Lung cancer cell lines were divided into high‐, intermediate‐ and low‐AXL groups based on the tertiles of the basal AXL expression level and we visualized the differential expression between the high‐ and low‐AXL groups in the KEGG Hippo signaling pathway." (PMID 33207077, 2021).
lung cancer (continued). "In breast and lung cancers, AXL overexpression activates the MAPK and PI3K signaling pathways to increase growth, survival, vascularization, and proliferation." (PMID 33283192, 2020). "This is the first report of a method to detect AXL expression on CTCs in patients with lung cancer combined with VM expression as a marker." (PMID 31999390, 2020). "Cancer-associated fibroblasts can also produce Gas6 following therapy leading to the migration of AXL-positive lung cancer cells." (PMID 31963783, 2020). "AXL is highly overexpressed in the resistant cells of erlotinib-treated lung cancer, and treatment of an erlotinib-resistant cell line with an AXL inhibitor restored cell sensitivity to erlotinib." (PMID 33396393, 2020). "We established the detection of AXL‐expressing in circulating tumor cells of lung cancer patients incorporating vimentin as a CTC marker in addition to cytokeratin." (PMID 31999390, 2020). "Axl receptor tyrosine kinase is involved in the growth and metastasis and is an indicator of poor prognosis in several cancers including lung cancers." (PMID 30744655, 2019). "PTBP1 was observed to be negatively correlated with AXL expression in lung cancer tissues (r = −0.7266, P < 0.01)." (PMID 31729427, 2019). "Along these lines, we utilized the natural antitumor compound YD to target AXL degradation which exhibits anti-proliferative activities against various human lung cancer cells by regulating AXL, SerpinB2, NNMT, and BMP422,39–42." (PMID 31043587, 2019). "As a result, up-regulation of AXL expression by PTBP1 siRNA was observed in other lung cancer cell lines, including A549 and H1299." (PMID 31729427, 2019). "The RTK AXL which binds to a secreted ligand Gas6 has been shown to be a rigidity sensor and facilitate a decrease in cellular stiffness in lung cancer." (PMID 31172946, 2019). "Individuals with EGFR-mutant lung cancers in acquired resistance to TKIs demonstrated increased expression of AXL and, in some cases, also of its ligand GAS6." (PMID 31815659, 2019). "Among them, AXL modulates actin polymerisation, promotes cell-matrix adhesion, connects with focal adhesions in lung cancer, Schwannoma or GBM cells, and is generally associated with a migratory phenotype." (PMID 32642659, 2019). "Recently, DS-1205, a new AXL inhibitor, was developed to overcome AXL-mediated resistance to EGFR-TKI in lung cancer." (PMID 31336846, 2019). "AXL activation and MED12 loss induced an EMT-like phenotype, which is associated with EGFR-TKI resistance in lung cancer." (PMID 29930762, 2018). "AXL inhibition results in decreased cell proliferation and metastasis of breast and lung cancer cells." (PMID 30386383, 2018). "In the subgroup of lung cancer with metastases to organs other than brain, high AXL and GAS6 expression accounted for nine of 32 (28.1%) in both markers." (PMID 28551766, 2017). "The YAP/TAZ/TEAD complex was shown to regulate AXL expression in gallbladder, hepatocellular carcinoma, and lung cancers." (PMID 28251492, 2017). "These miRNAs bind to the 3′-UTR of the AXL gene to negatively regulate its expression in breast, colorectal, head and neck, hepatocellular carcinoma, and lung cancer cell lines." (PMID 28251492, 2017). "Previous studies established a relationship between high AXL expression and malignancy in lung cancer." (PMID 29259259, 2017). "Previous studies have established a correlation between high expression of AXL and malignant progression and metastasis in lung cancer." (PMID 29259259, 2017).
lung cancer (continued). "In a recent study it has been reported that in cellular lung cancer models of acquired resistance to the EGFR TKI erlotinib there was an increased activation of AXL and induction of an EMT-like state." (PMID 25966280, 2015). "Our study findings thus show that AUY922 is a promising therapeutic option for MET- and AXL-mediated resistance to EGFR-TKI in lung cancer." (PMID 25780909, 2015). "In summary, AUY922 exerts effective control over malignant phenotypes that are driven by MET and AXL, including drug resistance, in lung cancer." (PMID 25780909, 2015). "Overexpression of AXL has been observed in approximately 60% of NSCLC cell lines, and AXL is also highly expressed in a significant fraction of primary lung cancers." (PMID 25337673, 2014). "Analogous to our findings with erlotinib resistance, at least in vitro crizotinib resistance in ALK-translocation positive lung cancer models also appears to be mediated by an EMT transition accompanied by AXL overexpression." (PMID 25337673, 2014). "AXL was thought to play a key role in the acquisition of the resistance to EGFR inhibitor in lung cancer." (PMID 24344100, 2013). "Recently the RTK, AXL has been found to have a key role in determining lung cancer chemosensitivity." (PMID 23300999, 2013). "Bavdegalutamide, a proteolysis-targeting chimera (PROTAC) degrader of the androgen receptor (AR), shows promise in prostate cancer treatment, while TAM-IN-2, a TAM receptor inhibitor, effectively blocks Gas6-induced AXL activation and suppresses lung cancer progression." (PMID 40573405, 2025). "Concurrently, to determine whether mfhAXL CAR-T cells could inhibit the growth of AXL-positive lung cancer, we established a subcutaneous tumor model by injecting mice with luciferase-overexpressing A549 cells (A549-LUC)." (PMID 40299452, 2025). "To evaluate the antitumor efficacy of mfhAXL CAR-T cells in the treatment of solid tumors, we conducted a cytotoxicity assay using mfhAXL CAR-T and untransfected T cells (control T) against AXL-positive lung cancer cells (A549) and pancreatic cancer cells (Panc-1) at different E/T ratios." (PMID 40299452, 2025). "Indeed, nuclear AXL ICD was detected in pancreatic and lung cancer cells treated with the proteasome inhibitor, suggesting that two competing mechanisms, nuclear import and proteasome-dependent degradation, define AXL ICD fate." (PMID 40044635, 2025). "AXL, a transmembrane receptor and a member of the TAM family of receptor tyrosine kinases, is implicated in many steps of the metastatic cascade and has emerged as a promising therapeutic target for many tumours, including lung cancer." (PMID 41471387, 2025). "Also in lung cancer, it has been shown that PTBP1 binds to the 5′ UTR of the mRNA of the transmembrane receptor tyrosine kinase AXL causing a decrease in its stability and thus affecting tumour progression." (PMID 40579921, 2025). "As these pathways exhibit compensatory activation upon cabozantinib treatment in resistant cells, we investigated whether VEGFC/KDR/NRP2 knockdown elicited a decrease in FGF/YAP/TAZ/AXL expression in resistant lung cancer cells." (PMID 40843133, 2025). "Toceranib phosphate is also capable of blocking PDGFR, VEGFR, Flt-3, CSF1R, RET, ALK, and AXL, which may provide potential benefits for dogs with primary lung cancer." (PMID 39902337, 2024). "Additionally, our findings follow previous results showing that NPS-1034 plays a crucial regulatory role as an inhibitor in both the MET and AXL pathways in solid tumors, such as lung cancer and gastric cancer." (PMID 39451232, 2024). "In lung cancer, AXL expression was found to be directly linked to EGFR signaling, involving the MAPK and c-Jun pathway activation, again suggesting the involvement of HER ligands in AXL upregulation." (PMID 39000238, 2024). "This study reveals a connection between MIG6 and AXL in lung cancer." (PMID 37834326, 2023).
lung cancer (continued). "Detection of AXL+ CTCs was reported in lung cancer using an automated micro‐cavity array system." (PMID 38132919, 2023). "Also supportive of a link between AXL and SARS‐CoV‐2 is an observed upregulation in AXL expression following SARS‐CoV‐2 infection in a non‐small cell lung cancer patient." (PMID 37193304, 2023). "This is in line with lung cancer data where AXL inhibitors could enhance the effect of EGFR-targeted therapies in resistant AXLhigh cells." (PMID 35332208, 2022). "Notably, more cases with higher AXL expression were found by IHC in EGFR tyrosine kinase inhibitor (EGFR TKI)-resistant lung cancer tissues." (PMID 36261437, 2022). "Additionally, FGFR1 was reported to co-stimulate T cells, and targeting of AXL sensitised lung cancer cells to lymphocyte-mediated cytotoxicity." (PMID 35727847, 2022). "In osimertinib-resistant lung cancer cell lines harboring T790M mutation that we established, expression of multiple EGFR family proteins and MET was markedly reduced, whereas expression of AXL, CDCP1 and SRC was augmented along with activation of AKT." (PMID 35643725, 2022). "For example, AXL expression has been associated with adverse clinical outcomes upon treatment with the third-generation EGFR inhibitor Osimertinib, which is also effective against lung carcinoma cells with secondary T790M mutations." (PMID 35572601, 2022). "Further, AXL expression was associated with JAK1-STAT3 signaling in treatment-naïve tumors and lung cancer patient-derived organoids with high levels of AXL and JAK1 were sensitive to combined treatment with AXL kinase inhibitor TP-0903 and JAK inhibitor ruxolitinib." (PMID 34830794, 2021). "In lung cancer, the AXL tyrosine kinase receptor is often overexpressed." (PMID 33546236, 2021). "The present study results showed that the subcritical water extract from ABM’s mycelium significantly decreases the expression of immune checkpoint molecules and Axl receptor tyrosine kinase in lung cancer cells and enhances the expression of surface maturation makers in dendritic cells." (PMID 34436128, 2021). "Specifically, in EGFR-mutated lung cancer cell lines expressing high levels of AXL (PC9 and HCC4011 cells), a small population of tumor cells tolerant to osimertinib emerged as persisters by restoring the survival signal generated by AXL." (PMID 34202566, 2021). "Subsequent to the first report of IGF-1R activation in 2010, AXL, Notch3, and fibroblast growth factor receptor 3 (FGFR3) are identified as receptor tyrosine kinases (RTKs) that cause drug tolerance in lung cancers with EGFR mutations." (PMID 34202566, 2021). "Accordingly, high levels of AXL expression in lung cancer cells correlated with intrinsic resistance to killing by both natural killer cells and cytotoxic T lymphocytes and this phenotype could be reversed by treatment with the AXL inhibitor R428." (PMID 34830794, 2021). "Moreover, using isogenic lung cancer cell pairs, we also found that doxorubicin treatment induced YAP nuclear translocation in mesenchymal‐type lung cancer cells to induce AXL expression." (PMID 33207077, 2021). "GLT21T is an aptamer targeted to tyrosine kinase receptor AXL that is overexpressed in lung cancer." (PMID 34138386, 2021). "Our results indicate that a doxorubicin‐induced increase in TGFβ expression contributes to YAP‐dependent AXL induction in mesenchymal‐type lung cancer cells, suggesting that alterations in EMT lead to chemoresistance by enhancing YAP‐dependent survival gene responses." (PMID 33207077, 2021). "Based on these results, we hypothesized that increased TGFβ‐SMAD signaling in mesenchymal‐type lung cancer cells after doxorubicin treatment potentiates YAP‐dependent AXL expression." (PMID 33207077, 2021). "Thus, it would be interesting to quantify miR‐34a levels upon doxorubicin treatment to characterize the role of miR‐34a on AXL expression in mesenchymal‐type lung cancer cells compared with epithelial cancer cells." (PMID 33207077, 2021).
lung cancer (continued). "To chemically probe the function of AXL in the context of collateral gefitinib resistance, we used YD, an antitumor agent we previously characterized to have concurrent AXL-dependent inhibitory mode-of-action in addition to having EGFR-targeting activity in gefitinib-resistant lung cancer models." (PMID 33850249, 2021). "High coexpression of AXL and GAS6 is a risk factor for poor survival in lung cancer patients." (PMID 32051483, 2020). "For example, AGR3 has been shown to facilitate the stemness of colorectal cancer by regulating Wnt/β-catenin signaling; STC2 has been shown to be involved in resistance to treatment with EGFR tyrosine kinase inhibitors and to promote the progression of lung cancer by regulating JUN/AXL signaling." (PMID 33680908, 2020). "DAXL-88 decreased AXL signaling and migration of ovarian and lung cancer cell lines." (PMID 32148495, 2020). "Gas6/AxL can induce invasion and survival during prostate cancer cell bone marrow metastasis, and also promotes invasion and metastasis of gastric cancer and lung cancer." (PMID 31110076, 2019). "This is the first report that SPRY4 might be a potential negative regulator of AXL signaling in lung cancer with driver oncogenes that is treated with osimertinib." (PMID 30651547, 2019). "In addition, in lung cancer cells acquiring resistance to gefitinib or erlotinib due to AXL, it is highly likely that up-regulation of PTBP1 would recover their drug sensitivity." (PMID 31729427, 2019). "Here, the authors show that AXL, which is activated by osimertinib, can promote the emergence of tolerant lung cancer cell thus conferring resistance to osimertinib and propose the combination of Osimertinib with AXL inhibitor as a potential therapeutic approach in such resistant cancers." (PMID 30651547, 2019). "There are various studies on AXL in several cancers such as lung cancer." (PMID 30386383, 2018). "Because tumors with stem-like features have been shown to lead to poor survival and resistance to therapies, AXL strong expression in our lung cancer patients may promote such features and contribute to their poorer prognosis." (PMID 27100677, 2016). "Recent studies AXL to be a marker for poor prognosis in lung cancers, breast cancers, pancreatic cancer, renal cell carcinoma and ovarian cancer, and for treatment resistance in lung cancers, gastrointestinal stromal tumor, esophageal cancer, and ovarian cancer." (PMID 27100677, 2016). "In lung cancer, upregulation of AXL could promote cell growth and motility and may result in resistance to both targeted therapies and conventional chemotherapy in lung cancer." (PMID 26942465, 2016). "Although AXL has been shown to mediate stem-like behavior in other solid tumors such as breast cancer, glioblastoma, and cutaneous squamous cell carcinoma, this is a new finding in lung cancer." (PMID 27100677, 2016). "Moreover, high levels of AXL are involved in crizotinib (ALK inhibitor) resistance in lung cancer patients and contribute to FLT3 inhibitor resistance in acute myeloid leukemia (AML)." (PMID 27590506, 2016). "Binds to the extracellular domain of AXL to inhibit its catalytic activity in lung cancer." (PMID 25337673, 2014). "Several studies suggest that overexpression of AXL may result in resistance to both targeted therapies and conventional chemotherapy in different models, such as lung cancer, breast cancer, esophageal carcinoma, gastrointestinal stromal tumors, and AML." (PMID 25337673, 2014).